RNU6-804P (RNA, U6 small nuclear 804, pseudogene)
Gene: Small nuclear RNA gene on chromosome 5 (86,663,144 to 86,663,250, reverse strand). Ensembl gene ENSG00000207013.
Homologues: Orthologues: chimpanzee U6 (100% identical), macaque U6 (93% identical), dog U6 (79% identical), rabbit U6 (78% identical), pig U6 (76% identical), mouse Gm22500 (73% identical), rat LOC120095708 (68% identical). Paralogues in human: RNU6-1060P (91% identical), RNU6-1152P (91% identical), RNU6-15P (90% identical), RNU6-19P (90% identical), RNU6-10P (89% identical), RNU6-116P (89% identical), RNU6-12P (89% identical), RNU6-13P (89% identical), RNU6-14P (89% identical), RNU6-16P (89% identical), RNU6-211P (89% identical), RNU6-31P (89% identical), and 1282 more.